MTOR (mechanistic target of rapamycin kinase)
Diseases named in the same sentence as MTOR in open-access papers (continued):
Sharing a sentence is not in itself a finding about the gene and the disease.
cancer (continued). "It is well-known that mTOR has been extensively considered a very important target for cancer therapy, and many synthesized mTORC1 inhibitors, rapamycin derivatives such as RAD001, CCI-779, have been tested for cancer patients in clinic." (PMID 28061838, 2017). "Meanwhile, metformin, a drug with well-established safety profile routinely used in type II diabetes patients, has been discovered as a potential anti-cancer agent by reducing mTOR activity in experimental animal models." (PMID 28822012, 2017). "We therefore examined the possibility that Andro also induces cell death through regulating the Akt /mTOR signaling, a major pathway in the growth and survival of cancer cells." (PMID 28412728, 2017). "In the study, we initially demonstrated that PI3K/AKT/mTOR pathway was aberrant in SCLC cell lines by mining the Cancer Cell Line Encyclopedia (CCLE) database." (PMID 29290965, 2017). "Our results imply that inhibition of NOS1 by either genetic or pharmacologic methods can inhibit the AKT/mTOR pathway and decrease chemoresistance displayed by cancer cells." (PMID 28243469, 2017). "Dysregulated genes were significantly enriched in pathways related to cancer, mTOR signaling and cell cycle signaling." (PMID 28477009, 2017). "In the mTOR inhibitor group, all patients who died of cancer already had advanced disease during diagnosis." (PMID 28160552, 2017). "Several studies have shown that activation of Akt/mTOR/70S6K and 4EBP1 signaling is related to the augmentation of mitochondrial activity, and is involved in the cytoskeleton-based migration of cancer cells." (PMID 28107184, 2017). "A mutation in the PTEN gene or a downregulation of PTEN protein production are frequent occurrences in several types of cancer, and lead to activation of the AKT/mTOR signaling pathway, which is associated with a poor clinical prognosis." (PMID 28243469, 2017). "As described in this review, Deptor appears to play an important role in the pathogenesis of many types of cancers, mainly through its role in controlling the activity of mTOR." (PMID 28086984, 2017). "Two mammalian target of rapamycin (mTOR) inhibitors, everolimus and temsirolimus, have been approved for treatment of cancer." (PMID 28698765, 2017). "Although the precise underlying mechanism(s) have not yet been fully elucidated, increasing evidence indicates that the P13K/Akt/mTOR pathway plays a crucial role in the survival and survival of cancer cells." (PMID 29069736, 2017). "FBXW7, which is regulated by miR-223, has been identified as a tumor suppressor gene in several cancers, and plays key roles in modulating the degradation of various onco-protein substrates, including c-Myc, cyclinE, Notch, c-Jun, mTOR, and MCL1." (PMID 28507201, 2017). "Based on these findings, several investigations explored the potential synergy between mTOR inhibitors and cancer immunotherapy." (PMID 29156850, 2017). "Our findings highlight the importance of carefully monitoring PLK1-, MTOR-, and autophagy- activities in clinical studies, to identify leads for cancer therapy design." (PMID 28102733, 2017). "Calorie restriction is also a potent way of inhibiting of cancer initiation and progression through the same pathways as above and also through a decrease in mTOR signaling, decreased growth factor signaling and decreased vascular perturbations." (PMID 28966806, 2017). "PTEN loss and subsequent activation of the PI3K/Akt signaling promotes the activation of mTOR signaling, which is hyperactive in many cancers." (PMID 28306514, 2017). "MTOR is constitutively activated in various types of human cancers development, and mTOR signaling networks have emerged as attractive targets for novel anticancer therapies." (PMID 28186966, 2017). "As the center of PI3K pathways, mammalian target of rapamycin (mTOR) regulates multiple processes including proliferation, survival, and migration of cancer cells." (PMID 28544785, 2017).
cancer (continued). "Piperlonguminine, from the long pepper (Piper longum), possesses anti-tumor activity and suppresses the phosphorylation of AKT/mTOR, thereby upregulating ROS levels in several cancer cells, such as 786-O, PC-3, and MCF-7 cell lines." (PMID 29209152, 2017). "To date, precision therapeutic strategies, mTOR inhibition included, are designed based on the concept of oncogene addiction, in which the growth and survival of cancer cells can be often impaired once one single oncogene is inhibited." (PMID 28822012, 2017). "AZD8055 is a novel ATP-competitive mTOR kinase inhibitor that acts on the PI3K/AKT/mTOR pathway to inhibit cancer cell proliferation and/or induce cancer cell death." (PMID 28507275, 2017). "Preclinical studies demonstrated that the RAS/RAF/ERK and PI3K/AKT/mTOR pathway are potential therapeutic targets for various types of cancer." (PMID 28423618, 2017). "As a result, retrospective studies based on institutional experiences, such as our study, are still an attractive option for providing further knowledge about the role of mTOR inhibitor for preventing or treating post-transplant cancers." (PMID 28160552, 2017). "The feedback activation of AKT plays an important role in the unsatisfactory clinical results of mTOR inhibitor in cancer treatment." (PMID 29177004, 2017). "The mechanism of action of mTOR inhibitors can be multifactorial: inhibiting growth, angiogenesis, increasing apoptosis and altering metabolism within cancer cells and we aimed to study these features." (PMID 29371953, 2017). "mTOR inhibitors have also demonstrated anti-cancer activity in patients, albeit limited, increasing median overall survival by a few months." (PMID 29104248, 2017). "Mammalian target of rapamycin (mTOR) is the central player of the phosphatidylinositol 3-kinase (PI3K)-Akt-mTOR cascade, which is vital for malignant transformation and cancer progression." (PMID 28938571, 2017). "The phosphatidyl inositol 3 kinase (PI3K), AKT and mammalian target of rapamycin (mTOR) signal transduction pathway is frequently de-regulated and activated in human cancer and is an important therapeutic target." (PMID 28806782, 2017). "Currently several combination treatments of mTor- and Ras-pathway inhibitors are being tested in cancer therapy." (PMID 28562352, 2017). "On the other hand, information on the use of mTOR inhibitors with CNI minimization in post-transplant cancers was scarce." (PMID 28160552, 2017). "For example, metformin, a novel drug candidate for cancer prevention, is proved to inhibit mTOR signaling, and low expression of organic cation transporter 3 (OCT3/SLC22A3), a metformin uptake transporter causes resistance to metformin." (PMID 28822012, 2017). "The limited therapeutic potential of everolimus in cancer cells has been attributed to Akt activation due to feedback loops relief following mTOR inhibition." (PMID 28454119, 2017). "mTOR is a serine or threonine protein kinase that regulates growth, proliferation, survival, protein synthesis and is a target for anti-cancer agents." (PMID 29137114, 2017). "In some cancer models mTOR is pointed out as a regulator of MCT1 expression and PI3K/Akt/mTOR pathway is also a regulator of VEGF expression." (PMID 29137304, 2017). "Our data provide rationale for potential use of mTOR inhibitors in combination with docetaxel in these cancers." (PMID 28615679, 2017). "As previous reports demonstrated, the overexpression of LAT-1 can promote cancer growth via mammalian target-of-rapamycin (mTOR) and serve as a prognostic factor in PDAC." (PMID 29096620, 2017). "As one of essential signaling cascades characterized well in stem cell differentiation and proliferation, Sonic Hedgehog (SHH) pathway interacts with other cancer-associated signaling molecules like RAS/RAF/MEK/ERK, PI3K/AKT/mTOR, EGFR, and Notch9." (PMID 28507311, 2017).
cancer (continued). "Metformin and rapamycin are two FDA-approved mTOR inhibitors proposed for this purpose, exhibiting significant anti-cancer and anti-aging properties beyond their current clinical applications." (PMID 29165314, 2017). "mTOR inhibitors like Rapamycin and its analogs are widely used as potential anti-tumour agents, some already approved for clinical use in cancer therapy." (PMID 29050357, 2017). "Protein synthesis in cancer cells is sustained, at least partly, by the constitutive activation of mTOR signaling." (PMID 28878358, 2017). "The translationally controlled tumor protein (TCTP) is upregulated in a range of cancer cell types, in part, by the activation of the mechanistic target of rapamycin (mTOR)." (PMID 27813490, 2017). "mTOR is a highly conserved protein kinase and plays a central role in many types of cancer progression." (PMID 28176801, 2017). "A number of targeted cancer treatments in both clinical use and development target pathways that impact protein translation through mTOR inhibition." (PMID 28968974, 2017). "The PI3K/AKT/mTOR pathway, which is an important intracellular signaling pathway in cell cycle regulation, is directly related to cellular quiescence, proliferation, cancer, and longevity." (PMID 29179457, 2017). "It was reported that signaling molecules such as EGFR, Ras, PKC, AKT/PKB and mTOR, were found to play important roles in human cancer cells and were involved in cell proliferation, differentiation and survival." (PMID 29254483, 2017). "In cancer cells, the synergistic effect induced by enhanced E2F and mTOR activities changed the gene expression of some components in cell proliferation/survival signaling, such as Bcl2l1 and insulin-like growth factor 1 receptor (Igf1r)." (PMID 28076433, 2017). "PTEN and the AKT/mTOR signaling pathway are promising targets for improving the chemotherapeutic treatment of cancer." (PMID 28243469, 2017). "c-Myc can be regulated by the PTEN, LKB1, AKT and mTOR pathway at transcriptional or posttranscriptional levels in cancer cells." (PMID 29228674, 2017). "There has been emerging data showing that mTOR pathway plays a significant role in the development of different types of cancers." (PMID 28160552, 2017). "Finally, the anti-tumor potency associated with down-regulation of GLUT-1 by FGFR1 and AKT/mTOR co-targeted inhibition was confirmed also in vivo, further strengthening the contention that tackling on cancer glucose metabolism may offer a new therapeutic option for the treatment of SQCLC." (PMID 29190880, 2017). "The specific distribution of p-mTOR indicates that this molecule is involved not only in growth control but also in tubular structuring of normal and cancer tissues." (PMID 28831205, 2017). "Among them, the PI3K/mTOR pathway is the most frequently activated, which plays a central role in cancer initiation and progression." (PMID 28822012, 2017). "ErbB (p-value = 0.002), proteoglycan in cancer (p-value = 0.006) and mTOR (p-value = 0.01) signaling pathways are the top pathways involving gene targets for this miRNA." (PMID 28364128, 2017). "The PI3K-Akt-mTOR signaling pathway is one of them, which was found frequently activated in different cancers." (PMID 28218676, 2017). "The PI3K-Akt-mTOR signaling pathway plays an important role in the carcinogenesis of common cancers." (PMID 29212166, 2017). "With the concurrent activation of AMPK and MTOR in cancer cells, the ribosomal protein synthesis and translation processes are activated along with an operational TCA cycle, putatively fed by beta oxidation of fatty acids and recycled glutamine from CAFs." (PMID 28969664, 2017). "In many cancers the protein kinase mammalian target of rapamycin (mTOR) is hyperactivated, leading to an increase in the phosphorylation of several downstream targets." (PMID 29233971, 2017).
cancer (continued). "According to the name of mTOR, its target is rapamycin, which has been utilized for cancer therapy, such as its derivative RAD001 which is used in the treatment of renal cancer." (PMID 28320471, 2017). "mTOR deregulation occurs in various human diseases, including cancer, metabolic disorders, and neurodegeneration." (PMID 28973975, 2017). "mTOR signaling exerts significant positive regulation of cell proliferation and tumorigenesis in diverse cancers, and it is frequently aberrantly activated in cancers." (PMID 28126011, 2017). "Autophagy is constitutively activated in cancer cells due to the deregulation of PI3K/Akt/mTOR signaling pathway, which enables them to adapt to hypo-nutrient microenvironment and exhibit the robust proliferation at the pre-metastatic niche." (PMID 28279189, 2017). "During cancer cell metastasis, mTOR signaling pathway plays a critical role in cancer cell metastasis, and is aberrantly regulated." (PMID 28178668, 2017). "Combining mTOR inhibitors with other drugs has shown promise in treatment of certain drug-resistant cancers." (PMID 29100331, 2017). "Actually, it has recently been suggested a novel mechanism of cancer cell death by increasing the gluconeogenesis pathway activity via mTOR inhibitors." (PMID 28042959, 2017). "Epidermal growth factor receptor (EGFR) activation events and the mammalian target of rampamycin (mTOR) are considered important therapeutic targets in alleviating cancer conditions." (PMID 29234489, 2017). "Phosphatidylinositol 3-kinase/Protein kinase B/Mammalian target of rapamycin (PI3K/Akt/mTOR) signaling pathway is abnormally active in the growth and proliferation of cancer cells." (PMID 29088090, 2017). "AT406-induced cytotoxicity and apoptosis were again potentiated with mTOR knockdown in the primary cancer cells." (PMID 28036295, 2017). "Targeting the mTOR pathway has currently emerged as an interesting tool to control cancer with nutraceuticals, since mTOR promotes tumorigenesis." (PMID 28146060, 2017). "The mTOR/p70s6k signaling pathway regulates the survival and cell proliferation of many tumors and is commonly active in various cancers including EC." (PMID 28487599, 2017). "The top pathways these genes are a part of include “pathways in cancer”, “mTOR signaling”, and “TNF signaling”." (PMID 28768481, 2017). "Since mTOR pathway regulates proliferation, metastasis and is frequently activated in many kinds of cancers including NPC, we examined the correlation between BMP2 expression and the key substrates of mTOR signaling pathway using western blotting assay." (PMID 28455969, 2017). "The pathway of mTOR is upregulated in many types of cancerand mTOR-targeted cancer therapy has been successfully applied in clinic." (PMID 28744216, 2017). "Significant interest in these agents remains due to reports of clinical activity in certain individuals and indications, and to the high frequency of PI3K/mTOR aberrations in cancer." (PMID 29299135, 2017). "It is possible that this effect of metformin on hTERT is mediated through the mTOR pathway, as inhibition of AKT/mTOR has been shown to suppress telomerase activity and hTERT mRNA expression in a number of cancers." (PMID 29340030, 2017). "Like the human cancer genomes, the ribosomal DNA copy number contracts in mTOR activated hematopoietic stem cells relative to normal stem cells." (PMID 28640831, 2017). "This drug discovery effort provides opportunities for precision medicine approaches to target mTOR for cancer therapy." (PMID 28822012, 2017). "Trafficking regulation of lysosomal anchored proteins in MDSCs such as mTOR and Rab GTPases provides a new direction for immunotherapy in cancer treatment." (PMID 28415797, 2017). "Previous studies have reported an association between mTOR inhibitor sensitivity and the basal level of p-4E-BP1 in cancer cells." (PMID 29290965, 2017). "The anti-angiogenic properties of mTOR inhibitors have also been illustrated in various cancer models in vivo." (PMID 29104248, 2017).
cancer (continued). "Translation of nuclear-encoded mitochondrial function-related genes, protein folding, and entry in mitochondrial sub-compartments are regulated by mTOR which is often found to be hyper-activated in cancer." (PMID 28373964, 2017). "In many types of cancer deregulation of mTOR is observed, which is a central regulator of cell proliferation." (PMID 29050357, 2017). "The PI3K/Akt/mTOR pathway is related to development of resistance to docetaxel in prostate and other cancers." (PMID 28903409, 2017). "Activation of PI3K/Akt/mTOR pathway is a central event in many types of cancer and represents a promising target for new treatment strategies." (PMID 28991258, 2017). "MTOR, a ubiquitously expressed serine/threonine (Ser/Thr) kinase, is reported to play a crucial role in cancer progression by regulating cell proliferation, metabolism, drug resistance and other biological processes." (PMID 28422725, 2017). "Accumulated evidence indicate that the mTOR pathway is essential for regulation of tumor cell motility, invasion, and cancer metastasis." (PMID 29234489, 2017). "Genistein affects mTOR signaling, leading to increased interest in its use in cancer prevention and treatment, but epigenetic modification of PRR5L has not been previously reported." (PMID 27539829, 2017). "The metabolic rewiring of cancer cells relies on a hierarchical oncogenic cascade involved in Akt/mammalian target of rapamycin (mTOR), mitogen-activated protein kinase (MAPK) signaling, and, essentially, a MYC dependent metabolic transcriptome." (PMID 28245597, 2017). "Our work suggests that expression of Snail with a concomitant reduction of 4E-BP1 accounts for the limited efficacy of mTOR inhibitors in cancer therapy." (PMID 29263324, 2017). "While some others showed that metformin perhaps played an important role in cancer progression via regulating the mTOR signaling pathway." (PMID 28406985, 2017). "NVP-BEZ235 (hereafter referred to as BEZ235) is a PI3K/mTOR dual inhibitor being tested as an anti-cancer therapeutic in various clinical trials." (PMID 28445155, 2017). "Aberrant transduction and regulation of mTOR signal pathway keep close with the occurrence and progression of many cancers." (PMID 29212287, 2017). "The dysregulation of mTOR-ACL is a tumorigenic mechanism important for fueling cancer cell growth and survival." (PMID 28362357, 2017). "Other important nutrient sensing pathway participants involved in both aging and cancer are mTOR and AMP Kinase (AMPK)." (PMID 28966806, 2017). "Methylation and silencing of miR-196b expression was reported to potentiate mTOR signaling in melanoma and other cancers." (PMID 28396701, 2017). "Mammalian target of rapamycin (mTOR), an atypical serine/threonine kinase, is activated in numerous cancers, regulating cell proliferation, growth, differentiation, migration, and survival." (PMID 28422725, 2017). "The third finding of p-mTOR staining in examined cancer tissues was intense p-mTOR staining in the periphery or invasive front of the tumor, which was seen in ACs of the lung, colon, and pancreas." (PMID 28831205, 2017). "Although there have been some case series concerning the use of mTOR inhibitors in kidney transplant recipients after cancer diagnosis, the main approach in these studies was the elimination of the CNIs." (PMID 28160552, 2017). "The function of csMVP was mediated through mTOR, FAK, ERK and Akt signaling pathways, which are associated with cancer cell survival and metastasis." (PMID 29038587, 2017).